MAP2 (microtubule associated protein 2)
Diseases named in the same sentence as MAP2 in open-access papers (continued):
Sharing a sentence is not in itself a finding about the gene and the disease.
autism spectrum disorder (1 paper, 2022). A spectrum of developmental disorders that includes autism, and Asperger syndrome. "A depletion of MAP2, even partial, could feasibly contribute to endophenotypes which characterize autism spectrum disorders, particularly with respect to synaptic plasticity." (PMID 36187353, 2022).
bladder cancer (1 paper, 2024). "FASN, MAP2 and BMP6 were highly expressed in bladder cancer, while GPC2, CNOT6L, GALNT12 and CARD10 were expressed at low levels in bladder cancer." (PMID 38218866, 2024).
bone osteosarcoma (1 paper, 2019). A usually aggressive malignant bone-forming mesenchymal neoplasm arising from the bone. "To demonstrate SR-cryoCLEM on mammalian cells, we cultured human bone osteosarcoma epithelial (U2OS) cells on top of EM grids and transfected the cells with plasmid encoding rsEGFP2 fused to microtubule-associated protein 2 (MAP2), prior to vitrification by plunge-freezing." (PMID 30718653, 2019).
cerebral artery occlusion (1 paper, 2023). "A recent study showed that cofilin rod formation is significantly increased in the cortical core and penumbra after transient middle cerebral artery occlusion, causing degradation of microtubule-associated protein-2 (MAP2) and apoptosis." (PMID 37190062, 2023).
cervical cancer (1 paper, 2019). A primary or metastatic malignant neoplasm involving the cervix. "Accordingly, we report here the endogenous MAP2 expression in cervical carcinoma cells, the downregulation of which was produced by the ectopic expression of 5p and 3p strands of miR34a and c in SiHa cells, respectively." (PMID 30696040, 2019). "The role of MAP2 in cell migration in cervical cancer is not well understood; however, it could be one of the genes that miR-34 family members regulate to achieve their function in the cells." (PMID 30696040, 2019). "MAP2 was shown to be overexpressed in cutaneous melanoma and is considered a specific marker for pulmonary carcinoid tumor and small-cell carcinoma; however, its biological function in cervical cancer tumorigenesis is poorly understood." (PMID 30696040, 2019). "A regulatory interaction between MAP2 and invasion in cervical carcinoma cells is yet to be demonstrated, although the functions of both in cell motility/invasion may suggest it." (PMID 30696040, 2019). "Our findings suggest a possible antioncogenic regulating role of 5p and 3p strands, and provide evidence of the possible involvement of MAP2, MMP2, and MPP9 in cervical cancer regulated by miR-34a-5p, miR-34a-3p, miR-34c-5p, and miR-34c-3p." (PMID 30696040, 2019).
co-infection (1 paper, 2016). "Transduction of MEFs with this MultiPrime virus resulted in cells with neuron-like morphology, which expressed the neuronal markers MAP2 and β-tubulin III 20 days after transduction, indistinguishable from co-infection with three lentiviruses each expressing one of the transcription factors." (PMID 27143231, 2016).
colon adenocarcinoma (1 paper, 2022). "We revealed the colon adenocarcinoma patients (COAD) with mutations of a CRs set (EP300, MSH6, NSD2 and TRRAP) mediate a better survival with low expression of MAP2 and could benefit from taxnes." (PMID 36180906, 2022).
COVID-19 (1 paper, 2021). A disease caused by infection with severe acute respiratory syndrome coronavirus 2. "To investigate the effects of COVID-19 on BIMs, we examined systemic levels of six previously validated BIMs—MAP2, NSE, GFAP, S100B, Syndecan-1 and UCHL1." (PMID 34838058, 2021). "Additionally, we found that BIMs (NSE, S100β, tau, MAP2) were higher in men compared to women with COVID-19." (PMID 34838058, 2021). "We found that levels of BIMs, specifically MAP2, NSE and S100β were significantly elevated in the acute phase of COVID-19." (PMID 34838058, 2021). "Plasma samples from 57 subjects at < 48 h of COVID-19 hospitalization, and 20 matched controls were interrogated for the levels of six BIMs—including GFAP, S100B, Syndecan-1, UCHLI, MAP2 and NSE, two EIMs—including sICAM1 and sVCAM1." (PMID 34838058, 2021). "We found that MAP2, NSE and S100B were higher after COVID-19 indicative of brain injury after COVID-19." (PMID 34838058, 2021). "Three BIMs: MAP2, NSE and S100B, two EIMs: sICAM1 and sVCAM1 and seven CCs: GRO IL10, sCD40L, IP10, IL1Ra, MCP1 and TNFα were significantly (p < 0.05) elevated in the COVID-19 cohort compared to controls." (PMID 34838058, 2021). "Increased levels of MAP2, NSE and S100B indicate neuronal and astrocytic injury after COVID-19." (PMID 34838058, 2021).
Creutzfeldt-Jakob disease (1 paper, 2012). "Western blots and IHC revealed that at the terminal stages of the diseases, MAP2 levels in the brain tissues of scrapie infected hamsters, a patient with genetic Creutzfeldt-Jakob disease (G114V gCJD) and a patient with fatal familial insomnia (FFI) were almost undetectable." (PMID 22272295, 2012).
demyelination (1 paper, 2016). "At 1 day after SCI, accumulation of APP and Aβ, the loss of the cytoskeletal proteins such as microtubule associated protein-2 (MAP-2), and axonal demyelination have been found both within and away from injury epicenter." (PMID 26858599, 2016).
ganglioglioma (1 paper, 2025). A well differentiated, slow growing neuroepithelial neoplasm composed of neoplastic, mature ganglion cells and neoplastic glial cells. "Ganglioglioma is characterized by the presence of true, well-formed ganglion cells with neuronal marker positivity (e.g., synaptophysin and MAP-2)." (PMID 41024929, 2025).
glioneuronal tumors (1 paper, 2021). "Looking in a supervised way at expression of particular differentiation markers commonly used for immunohistochemical analysis of glial/glioneuronal tumors, we found low GFAP expression, and modest levels of OLIG2, NeuN (RBFOX3), MAP2 and synaptophysin (SYP)." (PMID 34417833, 2021).
hematoma (1 paper, 2016). A hematoma is a collection of blood from a vascular structure into an extravascular space. "CEGI treatment significantly alleviated the neurobehavioral dysfunction, reduced the lateral ventricular enlargement, promoted hematoma absorption, effectively up-regulated MBP/MAP-2 expression, and ameliorated white matter fiber damage post-ICH induction." (PMID 27782218, 2016).
Hydrocephalus (1 paper, 2016). Hydrocephalus is an active distension of the ventricular system of the brain resulting from inadequate passage of CSF from its point of production within the cerebral ventricles to its point of absorption into the systemic circulation. "The beneficial effect of CEGI can be possibly attributed to the upregulation of MAP-2 and MBP expression, which could ameliorate myelin sheath and axon damage, and to the reduction of the lateral ventricular enlargement and prevention of hydrocephalus secondary to IVH/ICH." (PMID 27782218, 2016).
Hyperammonemia (1 paper, 2022). An increased concentration of ammonia in the blood. "We confirmed the decrease in Map2 expression during hyperammonemia in our model, which suggests that there is a significant dysregulation of neural structure in these animals." (PMID 35464767, 2022).
Insulin resistance (1 paper, 2016). Increased resistance towards insulin, that is, diminished effectiveness of insulin in reducing blood glucose levels. "The related mechanisms might be associated with improving mitochondrial dysfunction, insulin resistance and pathological changes including expressions of Aβ and MAP2." (PMID 27393392, 2016).
insulinomas (1 paper, 2017). "Differential expression of UCH-L1, MAP1B, MAP2, VCAN, CDK4 and PDX-1 was verified in more than 40 PNETs, including insulinomas and non-insulinomas by IHC but the expression of CaSR was only validated in 29 insulinomas." (PMID 28526880, 2017).
Intellectual disability (1 paper, 2023). "In several case reports of intellectual disability and neuropsychiatric disorders including ASD, a reduced level of MAP2 has been noted." (PMID 37108467, 2023).
knee osteoarthritis (1 paper, 2021). "In order to check expression of FKBP51 in nerves across Hoffa’s fat pad, double immunolabelling for FKBP51 (green) and MAP2 (red) were performed in tissue sections from patients with advanced knee osteoarthritis (grade IV)." (PMID 34571845, 2021).
lymph node metastasis (1 paper, 2024). "pT-status and lymph node metastasis did not correlate with MAP2 expression." (PMID 38310601, 2024).
meningitis (1 paper, 2022). A disorder characterized by acute inflammation of the meninges of the brain and/or spinal cord. "We quantified the fluorescent signal of MAP2 and Tau proteins over the whole area of the brain tissue sections, considering that we had previously assessed that the surface areas of the brain tissue sections do not vary significantly between rats from the sham and meningitis groups." (PMID 36036510, 2022).
mood disorder (1 paper, 2025). A cognitive disorder a disturbance in which the person's mood is hypothesized to be the main underlying feature. "Our findings however though exist quite preliminary in nature, the data retrieved relevant to cytoskeletal alteration linked MAP2 in mood disorders are insufficient for a secondary analysis." (PMID 41146953, 2025). "The study explained more feasible strategies to assess MAP2 levels of mood disorders via blood and CNS samples." (PMID 41146953, 2025).
myalgic encephalomyelitis (1 paper, 2022). "Interestingly, autoantibodies to tau, α-synuclein, microtubule associated protein-2, and others have been detected in the plasma of Gulf War veterans with myalgic encephalomyelitis/chronic fatigue syndrome." (PMID 35517047, 2022).
myopia (1 paper, 2016). "Among the mRNAs targeted by differentially expressed miRNAs, there were several (Prkar1a, Rims2, Map2, Gabarapl1, Htr7, Add3, Erc1, Nlgn1) which were involved in synapse formation and function suggesting that synaptic function was one of the biological processes affected in form-deprivation myopia." (PMID 27622715, 2016).
neuropathies (1 paper, 2019). "Although potential role of MAP2 isoforms in neuropathies cannot be excluded, it is clear that MAP2c does not form paired helical filaments or similar aggregates." (PMID 30884818, 2019).
Pain (1 paper, 2022). An unpleasant sensory and emotional experience associated with actual or potential tissue damage, or described in terms of such damage. "Under chronic neuropathic pain- (CNP-) induced allodynia, MWT50 decreased significantly (P < 0.05), and overexpression of MAP2, GAP43, and tau was also observed." (PMID 35915650, 2022).
pheochromocytoma (1 paper, 2025). "Both MAP-2 and β-III-tubulin displayed no notable expression trends over DPD 7–21, while β-III-tubulin still displayed 57% (n = 2, data not shown) expression in undifferentiated PC12 cells relative to DPD 7, likely a corollary to the known β-III-tubulin expression in pheochromocytoma." (PMID 41372543, 2025).
pneumococcal meningitis (1 paper, 2022). An acute purulent infection of the meninges and subarachnoid space caused by Streptococcus pneumoniae, most prevalent in children and adults over the age of 60. "The brain tissue sections of rats subjected to pneumococcal meningitis showed a significant decrease of MAP2 and Tau fluorescent signals over time, indicating a reduction of neuronal synaptic connections due to neuronal damage." (PMID 36036510, 2022).
psychosis (1 paper, 2013). "In the present series, we found better preservation of dentritic/MAP2-related elements in the hilus and CA3 of MTLE patients with psychosis." (PMID 24069608, 2013). "We hypothesize that an increased MAP2 immunoreactive dendritic arborisation especially in the hilus and CA3 of MTLE patients with psychosis could be related to our previous results of decreased mossy fiber sprouting in MTLE + P patients." (PMID 24069608, 2013).
retinoblastoma (1 paper, 2016). A malignant tumor that originates in the nuclear layer of the retina. "A MAP2 antibody was used to detect these macromolecular structures in retinoblastoma cells and tissue." (PMID 27798680, 2016).
scrapie (1 paper, 2012). A fatal disease of the nervous system in sheep and goats, characterized by pruritus, debility, and locomotor incoordination. "In addition, our dynamic analysis of scrapie-infected rodents identify that the disappearance of MAP2 seems to occur at the early stage of infection, as it reduces to undetectable level in the 20 dpi samples." (PMID 22272295, 2012).
sleeping sickness (1 paper, 2023). "In conclusion, polyalanine Pa-MAP1.9 and Pa-MAP2 presented activity against bloodstream forms of T. b. gambiense, thus encouraging further studies on the application of these peptides as a treatment for sleeping sickness." (PMID 37623715, 2023).
testicular tumor (1 paper, 2020). "We next detected the microtubule‐associated protein 2 (MAP2), a neuronal cytoskeleton regulator, in testicular tumor xenografts, and found that NR6A1 can promote MAP2 expression." (PMID 33034957, 2020). "Further, NR6A1 promoted neuronal marker protein MAP2 expression in RA‐induced neurodifferentiation of NT‐2 cells and testicular tumor xenografts." (PMID 33034957, 2020).
Zinc deficiency (1 paper, 2012). A deficiency of the essential metal Zinc; an essential cofactor for many enzymes. "Zinc deficiency may also lower levels of α- and β-tubulin, MAP2 expression and impair MT polymerization." (PMID 22457776, 2012). "Zinc deficiency effects on lowered MT polymerization rates are apparently mediated through decreased electrostatic attraction between tubulin dimers, as well as decreased expression of MAP-tau, MAP2, and potential lowering of MAP-tau binding to MTs." (PMID 22457776, 2012).
tumor (86 papers, 2000 to 2025). "MAP2 knockdown modestly altered CD8+ T-cell–mediated killing under D + O + C or D + C treatment compared to control conditions, suggesting a potential role of MAP2 in shaping tumor susceptibility to immune cytotoxicity." (PMID 41256002, 2025). "Immunophenotypically, the tumor cells show strong expression of the neuronal markers neurofilament (NF) and microtubule-associated protein 2 (MAP2), along with faint expression of synaptophysin (SYN)." (PMID 40711574, 2025). "MAP2 is correlated with tumor grade and MAP2 high-expressing PCA is associated with an increased risk of biochemical recurrence after radical prostatectomy." (PMID 38310601, 2024). "Next, using the fractions estimated by CIBERSORT, we found the patients with MAP2 low expression or high expression showed significant difference in enrichment of tumor immune cell infiltration when MAP2 module mutations." (PMID 36180906, 2022). "There was no expression of oligodendrocyte transcriptor-2 (Olig-2), epidermal growth factor receptor (EGFR), neurofilament (NF), CD117, nestin or microtubule-associated protein 2 (MAP2) in the tumor cells." (PMID 24348765, 2014). "Similar results are seen for genes associated with tumor suppression and MAP2, considered to be anti-metastatic." (PMID 21510869, 2011). "Further ASPM has been implicated in tumor cell proliferation and growth MAP2 stabilizes and interacts with microtubules during the growth, differentiation, and development of neurons." (PMID 18541031, 2008). "In the tumor cells at metastatic locations, we detected meta-program IV (MAP2, GRIK2), a hallmark of neuron development, and meta-program I, the mesenchymal-neuroblast-like (MES-Nbt) state, which was enriched for genes related to the EMT such as ZEB1, ZEB2, and TEAD1." (PMID 41279557, 2025). "Similarly, it has been reported that the CD105 (endoglin) antibody was available for antiangiogenic tumor therapy, and that microtubule-associated protein-2 (MAP-2) antibody could elevate the therapeutic efficacy in spinal cord injury." (PMID 33066531, 2020). "The protrusions of astrocytic cells (GFAP+) were observed to spread from the interaction site into the tumor sphere, while this was observed less extensively for the neurons (MAP2+)." (PMID 40917877, 2025). "Within each tumor, we observed that taurine intensities were significantly higher in the more differentiated MAP2 + /VSNL1+ regions compared to the MAP2 + /VSNL1- areas (t-test p value < 0.01)." (PMID 38191555, 2024). "MAP2 expression was predominantly found at the interface between high-grade PINs and invasive tumor cells." (PMID 38310601, 2024). "MAP2 immunohistochemistry either revealed expression with a gradual loss of MAP2 expression leading to a patchy staining pattern or it was characterized by a rather uniform MAP2 staining in different tumor areas." (PMID 38310601, 2024). "The tumor cells were stained positively for some neurogenic makers, for instance S100, Syn, MAP2, NFP, Nestin, CD56, and SOX2, which highlighted the neural lineage differentiation of tumor cells." (PMID 36153506, 2022). "MAP2-positive cells were found in both conditions, and as already pointed out, many MAP2-immunolabeled IUE cells were found within the tumor." (PMID 36538906, 2022). "Analysis of tumor sections identified more evidence of decreased tumor proliferation (Ki-67) and elevated expression of neuronal maker MAP2 in the group with combined treatment." (PMID 35610201, 2022). "Antibodies against NeuN and MAP2 were used to further characterize the neuron-like component in the control as well as BRAFV600E/AktDD tumor tissue." (PMID 36538906, 2022). "MAP2 is widely found in neurons and neurogenic tumor cells, and its ability to interact with microtubules plays a critical role in neuronal morphogenesis, such as neurite initiation." (PMID 34660263, 2021). "In tumor sections, expression of Sox1, Sox9, and Map2 was obvious in undifferentiated cells and differentiated neural tissue." (PMID 33468253, 2021).